ELOVL4 (ELOVL fatty acid elongase 4)
Description:
Catalyzes the first and rate-limiting reaction of the four reactions that constitute the long-chain fatty acids elongation cycle. This endoplasmic reticulum-bound enzymatic process allows the addition of 2 carbons to the chain of long- and very long-chain fatty acids (VLCFAs) per cycle. Condensing enzyme that catalyzes the synthesis of very long chain saturated (VLC-SFA) and polyunsaturated (PUFA) fatty acids that are involved in multiple biological processes as precursors of membrane lipids and lipid mediators. May play a critical role in early brain and skin development.
Synonyms: CT118; ADMD; ISQMR; SCA34; STGD2; STGD3
Tractability: Antibody: UniProt predicts a signal peptide or a membrane-spanning region. PROTAC: ubiquitination databases record sites on it.
Target class: Enzyme; Transferase
Gene: Protein-coding gene on chromosome 6 (79,914,814 to 79,947,553, reverse strand). Ensembl gene ENSG00000118402.
Subcellular location: Endoplasmic reticulum membrane
Pathways (Reactome):
Metabolism: Synthesis of very long-chain fatty acyl-CoAs
Gene Ontology:
Molecular function: fatty acid elongase activity; protein binding; G protein-coupled photoreceptor activity
Biological process: fatty acid elongation, saturated fatty acid; very long-chain fatty acid biosynthetic process; fatty acid biosynthetic process; fatty acid elongation, monounsaturated fatty acid; fatty acid elongation, polyunsaturated fatty acid; sphingolipid biosynthetic process; circadian rhythm; detection of visible light; fatty acid elongation; long-chain fatty-acyl-CoA biosynthetic process; negative regulation of mini excitatory postsynaptic potential; positive regulation of inhibitory postsynaptic potential; short-term synaptic potentiation; unsaturated fatty acid biosynthetic process
Cellular component: endoplasmic reticulum; endoplasmic reticulum membrane; membrane
Genetic constraint (gnomAD): Loss-of-function variants: 17 observed, 39.3 expected, observed/expected ratio (o/e) 0.43, 90% interval 0.29 to 0.65. The upper end of that interval is the gene's LOEUF score, 0.65, which puts it in group 2 of 6, group 1 being the genes least tolerant of losing a copy. Missense variants: 273 observed, 362.58 expected, observed/expected ratio (o/e) 0.75, 90% interval 0.68 to 0.83. Synonymous variants: 108 observed, 123.25 expected, observed/expected ratio (o/e) 0.88, 90% interval 0.75 to 1.03.
Gene-disease validity (ClinGen):
ClinGen rates the evidence that ELOVL4 causes each of these diseases.
ELOVL4-related maculopathy (autosomal dominant): Definitive. Any maculopathy caused by a variant in the ELOVL4 gene.
Homologues: Orthologues: macaque ELOVL4 (98% identical), dog ELOVL4 (96% identical), rabbit ELOVL4 (96% identical), chimpanzee ELOVL4 (96% identical), rat Elovl4 (94% identical), pig ELOVL4 (93% identical), mouse Elovl4 (91% identical), guinea pig ELOVL4 (91% identical), tropical clawed frog elovl4 (69% identical), zebrafish elovl4b (66% identical), zebrafish elovl4a (65% identical). Paralogues in human: ELOVL7 (39% identical), ELOVL2 (38% identical), ELOVL5 (38% identical), ELOVL1 (36% identical), ELOVL3 (22% identical), ELOVL6 (21% identical).
Diseases named in the same sentence as ELOVL4 in open-access papers:
ELOVL4 is named in the same sentence as 90 diseases in open-access papers, as found by Europe PMC text mining. Sharing a sentence is not in itself a finding about the gene and the disease. The quoted sentences say what the papers report.
Stargardt disease (20 papers, 2007 to 2025). "Autosomal dominant inheritance of ELOVL4 nonsense mutations cause Stargardt’s Macular Dystrophy (STGD3), an aggressive form of macular dystrophy that causes early onset photoreceptor degeneration and blindness by the early twenties." (PMID 38850484, 2024). "ELOVL4 has been implicated in Stargardts disease and macular dystrophy and is expressed in photoreceptor inner segments, in agreement with the ISH localisation of miR-124, its predicted regulator." (PMID 20053268, 2010). "Stargardt disease 3 (STGD3) is a juvenile macular dystrophy caused by mutations in the elongase of very long-chain fatty acids-like 4 (ELOVL4) gene, which encodes an elongase involved in the production of extremely long-chain fatty acids." (PMID 21139992, 2010). "In Stargardt disease 3, decreased Elovl4 activity is associated with cell death through unknown mechanisms." (PMID 29321376, 2018). "Three different sets of mutations in ELOVL4 cause three distinct neurodegenerative diseases: Spinocerebellar Ataxia 34 (SCA34), Stargardt’s Macular Dystrophy (STGD3), and neuroichthyosis." (PMID 38850484, 2024). "Variants in ELOVL4 gen and PROM1 gen have also been described in Stargardt disease in an autosomal dominant pattern." (PMID 34051736, 2021). "Although this review focuses on STGD3 and ELOVL4 mutation-associated disorders, recessive STGD1 (also known as fundus flavimaculatus) represents the more prevalent cases of juvenile-onset Stargardt macular dystrophy diseases." (PMID 33556440, 2021). "Patients of the ABCA4 and ELOVL4 cohorts also exhibited other classical symptoms reported in Stargardt disease: dyschromatopsia, central scotoma, photophobia, and delayed dark adaptation." (PMID 34073554, 2021). "Patients with Stargardt 3 disease (STGD3), an early-onset macular dystrophy, have C-terminal ELOVL4 mutations that lead to a premature stop in ELOVL4 protein translation, creating a truncated transmembrane protein without an endoplasmic reticulum dilysine retention signal (KXKXX)." (PMID 38342437, 2024). "This is a new and emerging CRISPR tool for gene therapy with few reports published so far, but given its potential in correcting the vast majority of mutations that cause Stargardt disease, including the most common STGD3 5 bp deletion in ELOVL4, it is an incredibly exciting option for the future." (PMID 34439845, 2021). "In the case of Stargardt disease, a large proportion of mutations in ABCA4, ELOVL4 and PROM1 could be targeted with one or more of the currently described CRISPR-based approaches: genome editing, epigenetic repression, base editing or prime editing." (PMID 34439845, 2021). "Heterozygous inheritance of several different ELOVL4 mutations in exon 6 that cause early truncation of the ELOVL4 protein and loss of the ER-retention signal in the C-terminus leads to autosomal dominant Stargardt-like macular dystrophy (STGD3), an aggressive juvenile-onset macular degeneration." (PMID 34227061, 2021). "Specifically, Sanger sequencing of ABCA4, PRPH2/RDS-peripherin, and ELOVL4 was negative except for Proband 1, who had a heterozygous ABCA4 missense variant (c.2588G>C; p.Gly863Ala) and no family history of Stargardt disease or cone-rod dystrophy." (PMID 30116628, 2018).
ichthyosis (18 papers, 2014 to 2025). Disorders of cornification that are characterized by visible scaling and/or hyperkeratosis of most or all of the skin. "Biallelic ELOVL4 mutations lead to ichthyosis, spastic quadriplegia, and impaired intellectual development." (PMID 38540347, 2024). "Other mutations in ELOVL4 have been associated with spinocerebellar ataxia, dry eye, ichthyosis, mental retardation, nystagmus, poor eye contact, latent visual responses, reduced electroretinogram (ERG) responses, retinitis pigmentosa, and myopathy." (PMID 37513514, 2023). "Homozygous inheritance of other recessive ELOVL4 mutations that result in truncation of the ELOVL4 protein causes a neuro-ichthyotic syndrome characterized by severe seizures, intellectual disability, spasticity, ichthyosis, and early death." (PMID 34227061, 2021). "Heterozygous mutations in ELOVL4 gene cause Stargardt-like macular dystrophy and spinocerebellar ataxia type-34, while different homozygous mutations have been associated with ichthyosis, spastic quadriplegia, and mental retardation syndrome in three kindred." (PMID 33652762, 2021). "A distinct set of ELOVL4 mutations can cause a neurocutaneous disorder characterized by ichthyosis, seizures, spasticity, intellectual disability, and ichthyosis." (PMID 32054030, 2020). "Homozygous inheritance of three other recessive ELOVL4 mutations causes a devastating neuro-ichthyotic syndrome characterized by seizures, intellectual disability, spasticity, ichthyosis, and premature death." (PMID 32780351, 2020). "Homozygous inheritance of a different set of ELOVL4 mutations causes a more severe disease with infantile onset characterized by seizures, spasticity, intellectual disability, ichthyosis, and premature death." (PMID 31616255, 2019). "Homozygous inheritance of ELOVL4 mutations causes more severe disease characterized by seizures, intellectual disability, ichthyosis, and premature death." (PMID 28507511, 2017). "A rare neuro-ichthyotic disorder characterized by ichthyosis, spastic quadriplegia and intellectual disability and caused by recessive mutations in ELOVL4, encoding elongase-4 protein has recently been described." (PMID 24571530, 2014). "Finally, ELOVL4 neuro-ichthyotic syndrome, the most severe disease associated with ELOVL4 mutations, is characterized by seizures, spasticity, intellectual disability, ichthyosis, and early death." (PMID 32780351, 2020). "Homozygous inheritance of recessive ELOVL4 alleles that would lead to a severely truncated and presumably inactive ELOVL4 protein results in a much more severe neuro-ichthyotic disease characterized by seizures, spasticity, intellectual disability, ichthyosis, and early death." (PMID 34227061, 2021). "ELOVL4 dysfunction is involved in other disorders ranging from ichthyosis to spinocerebellar ataxia." (PMID 38342437, 2024). "Accordingly, humans carrying mutant alleles of ELOVL4, CYP4F22, or CERS3 develop a similar ichthyosis pathology as reported for ABHD5 and PNPLA1 deficiency due to the lack of ULC ω-hydroxy ceramides and AcylCer in the epidermis." (PMID 30361410, 2018). "Large decreases in or loss of acylceramide due to mutations in the genes involved in acylceramide synthesis (such as CERS3, CYP4F22 and ELOVL4) causes non-syndromic ARCI (CERS3 and CYP4F22) or a syndromic form of ichthyosis (ELOVL4) (refs 5, 8, 10, 12, 21)." (PMID 28248318, 2017). "ELOVL4‐related ichthyosis, spastic quadriplegia, and mental retardation (MIM 614457) an autosomal recessive disorder, characterized by ichthyosis, global developmental delay, epilepsy, and failure to thrive, has so far been described in nine families." (PMID 40590574, 2025). "ELOVL4 pathologies such as STGD3, ichthyosis, and spinocerebellar ataxia-34 highlight the importance of VLC-PUFAs in normal human development and function." (PMID 37513514, 2023).
retinal degeneration (18 papers, 2007 to 2024). Degeneration of the retina. "More recently, novel very-long fatty acids, longer than 28 carbon atoms, have been identified and chemically characterized as products of elongase Elovl4, coded by a gene whose defects have been found cause retinal degeneration in patients." (PMID 36978865, 2023). "Further evidence ruling out Elovl4 haploinsufficiency as the cause of STGD3 retinal degeneration came when transgenic and knock-in models were generated expressing disease-associated mutations." (PMID 34439845, 2021). "Mutation, loss, or downregulation of ELOVL4 is linked to retinal degeneration." (PMID 35508275, 2022). "Heterozygous inheritance of one set of autosomal dominant ELOVL4 mutations that leads to truncation of the ELOVL4 protein causes Stargardt-like macular dystrophy (STGD3), an aggressive juvenile-onset retinal degeneration." (PMID 31616255, 2019). "This goes along with the observed positive correlation between expression levels of mutant ELOVL4 and the severity of retinal degeneration in transgenic mouse models expressing increasing amounts of the human mutant ELOVL4 protein (TG1, TG1-2, TG2 and TG3)." (PMID 29293603, 2018). "Disruption of REP-1, PROM1, ELOVL4, or ABCA4, each involved in lipid processing, causes early-onset retinal degeneration." (PMID 29321376, 2018). "This preservation of retinal morphology and function despite the presence of mutant ELOVL4 was surprising, since rod-dominant transgenic mouse models indeed showed signs of retinal degeneration." (PMID 29293603, 2018). "Elovl4 KO mice whose skin phenotype was rescued by the expression of an Elovl4 transgene in their skin suffered from severe seizures and died in the first month of life before retinal degeneration phenotypes became apparent." (PMID 38342437, 2024). "Elovl4 expression was downregulated (p < 0.05, unpaired t-test) throughout retinal degeneration." (PMID 36670960, 2022). "The results of our study show that high DHA levels in the retinas of mice overexpressing the mutated ELOVL4 transgene do not slow or prevent the retinal degeneration." (PMID 19536303, 2009). "In contrast to other previously known SCA34-causing ELOVL4 mutations, which showed no retinal degeneration, the I171T ELOVL4 mutation was associated with retinitis pigmentosa, a degenerative retinal disease, in 4 of the 10 family members examined (three males and one female)." (PMID 32780351, 2020). "However, a particularly intriguing question is why one set of ELOVL4 mutations would lead to a retinal degeneration with no other problems in the brain, while a different set of ELOVL4 mutations would cause spinocerebellar ataxia without any retinal involvement." (PMID 28507511, 2017). "Studies in transgenic mice expressing the mutant STGD3 form of ELOVL4 in photoreceptors showed lipofuscin accumulation, retinal degeneration and reduced ERG signals, all features of human STGD3." (PMID 17356513, 2007). "In contrast, the W246G ELOVL4 mutation did not affect VLC-PUFA levels in the retina, consistent with the absence of retinal degeneration in HET and MUT rats." (PMID 34227061, 2021). "Since patients with L168F ELOVL4 mutation do not have any reported retinal degeneration, we determined the effect of the L168F mutation on VLC-PUFA biosynthesis in HEK293 cells transduced with Myc-tagged Elovl4 variants (WT and L168F) or GFP and UT control cells supplemented with 20:5n3." (PMID 36464075, 2023). "However, this reduction in PC-VLC-PUFA content in the all-cone retina had no impact on morphology or function and did not accelerate retinal degeneration in the R91W;Nrl-/-;Elovl4 mice." (PMID 29293603, 2018). "To determine how the levels of VLC-PUFA and VLC-SFA species may be altered in SCA34 disease, we utilized two ELOVL4 mutations, L168F and W246G, which cause SCA34 with different ages of onset of disease and without any reported retinal degeneration in our experiments." (PMID 36464075, 2023).
retinal degeneration (continued). "The ability of these mutants to make some levels of VLC-PUFAs, which may be sufficient to preserve retinal structure, may explain why SCA34 patients do not have any reported retinal degeneration compared to STGD3 patients in which the STGD3 mutant ELOVL4 lacks VLC-PUFA biosynthesis." (PMID 36464075, 2023).
Ataxia (16 papers, 2017 to 2024). Ataxia refers to impaired coordination of voluntary muscle movement. "We subsequently performed the first dedicated literature review of ELOVL4-associated ataxia to gain further insights into genotype–phenotype relationships." (PMID 36696030, 2024). "The two additional affected individuals subsequently underwent the Sanger sequencing, confirming that they carried the variant, consistent with segregation of the ELOVL4 variant with ataxia in the family." (PMID 36696030, 2024). "This case highlights the potential clinical phenotypic variability for ELOVL4-associated disease, though it is plausible that this individual develops ataxia later in his life." (PMID 36696030, 2024). "The ELOVL4 variant, c.698C > T p.(Thr233Met), was reclassified as a likely pathogenic variant based on segregation with the clinical ataxia phenotype within the family." (PMID 36696030, 2024). "An individual with spinocerebellar ataxia with the same ELOVL4 variant from another family was subsequently identified." (PMID 36696030, 2024). "Spinocerebellar ataxia 34 (SCA34) is an autosomal dominant inherited disease characterized by age-related cerebellar degeneration and ataxia caused by mutations in the Elongation of Very Long Chain Fatty Acid-4 (ELOVL4) gene." (PMID 37568198, 2023). "Here we focused on the ELOVL4 p.W246G variant as this is associated with a pure cerebellar ataxia (SCA34) and was previously noted to be located close to ELOVL5 p.G230V in SCA38." (PMID 37199746, 2023). "Disruptions of ELOVL4 synthesis were implicated in dermatological disorders and different types of ataxias." (PMID 36005150, 2022). "In view of no changes in the major synaptic signal transduction pathways in this rat model of SCA-34 analyzed so far, further studies should address the specific role of ELOVL4 in cerebellar synaptic plasticity and the cause of ataxia." (PMID 34227061, 2021). "Based on these findings, we suggest that the W246G ELOVL4 mutation is likely to cause synaptic dysfunction that leads to the development of the ataxia and other CNS symptoms characteristic of SCA34." (PMID 34227061, 2021). "In 2019, another heterozygous ELOVL4 mutation, c.698C > T (p.T233M), was discovered in a patient with multisystem neurodegeneration, including ataxia and EKV skin lesions." (PMID 33556440, 2021). "Recently, a study of 10 affected members of an American family with a novel heterozygous ELOVL4 mutation (I171T) that results in spinocerebellar ataxia and retinitis pigmentosa was reported." (PMID 32780351, 2020). "This mutation causes a late-onset spinocerebellar ataxia similar to other SCA34-causing ELOVL4 mutations." (PMID 32780351, 2020). "Assessment of developmental patterns of ELOVL4 expression focused on brain regions associated with the CNS-related symptoms (seizures and ataxia) of diseases caused by ELOVL4 mutations: cortex, hippocampal formation, and cerebellum." (PMID 28507511, 2017). "Patients with the c.512T > C, (p.I171T) ELOVL4 variant show ataxia that may appear together with retinitis pigmentosa with or without EKV." (PMID 38850484, 2024). "Affected family members carry a transversion mutation, c.540G > C (p.L168F), in exon 4 of ELOVL4, which segregates with a skin phenotype consisting of early-onset patches of erythema and hyperkeratosis with the ataxia pathology manifesting in the fourth or fifth decade of life." (PMID 33556440, 2021). "Mutations of ELOVL5 or ELOVL4 cause spinocerebellar ataxia 38 and 34, respectively with common neurological symptoms which might be explained by the regional expression similarity between the two enzymes." (PMID 33994961, 2021). "Mutations in very long chain fatty acid elongase 4 and 5 (Elovl4 and ElovL5) are reported to cause spinocerebellar ataxia and accumulation of the branched-chain acid fatty acid was reported to be associated with Refsum disease caused by mutations in Phytanic acid alpha-oxidation (in AOA gene panel)." (PMID 33255407, 2020).